GFAP (glial fibrillary acidic protein)
Diseases named in the same sentence as GFAP in open-access papers (continued):
Sharing a sentence is not in itself a finding about the gene and the disease.
Stroke (continued). "Therefore, in the time window between 2 and 6 h after stroke onset, GFAP could be considered useful for differentiation between hemorrhagic and ischemic stroke." (PMID 31701356, 2020). "Furthermore, there are premises suggesting value of some biomarkers in the diagnosis of specific stroke types, such as cardioembolic stroke (vWF, TNFα), hemorrhagic stroke (GFAP, MMP-9), large- and small-artery disease (IL-6; TNFα), or lacunar stroke (Glu, GABA)." (PMID 31701356, 2020). "Ischemic insults cause pathological alteration of astrocytes, including the upregulation of GFAP, an important constituent of astrocytic intermediate filaments and hypertrophy of astrocytic processes, which can also be observed in patients who have had a stroke." (PMID 31382635, 2019). "Therefore, we investigated whether PTX3 affects GFAP+ astrocytes and/or Iba1+ microglia 28 days after experimental stroke." (PMID 30315331, 2018). "The increased expression of GFAP, VEGF, and MBP may help the brain to recover temporarily and offset its loss of function and thus may be the key to future treatment for patients who have experienced a stroke." (PMID 27597962, 2016). "Our finding of a potential link between astrocyte phenotype (GFAP upregulation and hypertrophic morphology) and stroke protection raises a tantalizing possibility that Smad1 ablation in the CNS may mimic the well-known preconditioning effect in raising the baseline levels of astrocyte reactivity." (PMID 26317208, 2015). "However, YFP+/GFAP+ cells were detected in the ipsilateral SVZ 30 days after stroke." (PMID 23118941, 2012). "Quantitative analysis revealed about 1% and 2% double-labeling of BrdU and GFAP in respective intact and infarcted side of NT-020-treated stroke brains, which were significantly lower than those seen in the intact (18%) and infarcted side (35%) of vehicle-treated stroke brains (** p < 0.0001)." (PMID 22837703, 2012). "Suitable for detecting neuronal injury biomarkers such as GFAP and NFL; plays an important role in early stroke diagnosis and prognosis assessment." (PMID 40066310, 2025). "The concentrations of these biomarkers are increased after stroke and help to determine the severity of brain injury, with NSE being a marker of neuronal death, GFAP for astrocytic injury and S100B for brain cell injury." (PMID 41296388, 2025). "In our research, PTI mice exhibited increased levels of stroke-related markers such as S100B, NT-pro BNP, and GFAP, compared to the Con mice, which is typically observed during IS." (PMID 40688396, 2025). "Several studies have confirmed these mechanisms and investigated stroke biomarkers, such as IL-6, S100B, NSE, D-Dimer and GFAP in T2DM populations, demonstrating their relevance to stroke risk." (PMID 41150802, 2025). "A key recommendation is to incorporate advanced diagnostic techniques, such as MRI and Transcranial Doppler Ultrasound, to improve the accuracy of stroke detection and validate biomarkers like S100B, GFAP and NSE as non-invasive stroke indicators." (PMID 41296388, 2025). "Patients admitted with a “stroke alert” exhibited significantly higher serum concentrations of both GFAP and UCH-L1 compared to those with stroke mimics, underscoring their potential role in the early differentiation of actual stroke cases." (PMID 40649119, 2025). "In the case of stroke chameleons, where stroke presents atypically and can be confused with other conditions, the use of biomarkers, such as GFAP and UCH-L1, can help differentiate between a real stroke and a stroke mimic even in the emergency department." (PMID 40649119, 2025). "After adjustment for infarct volume, peak level time points for GFAP and NFL were essentially unaltered, occurring at 77 h (3 days) for GFAP and > 8 days for NFL, t-tau, and UCHL1 after stroke onset." (PMID 40900222, 2025).
Stroke (continued). "The results of this systematic review, along with findings from existing literature, indicate that S100B, GFAP and NSE hold promise as biomarkers for brain injury in stroke, particularly in individuals with T2DM." (PMID 41150802, 2025). "GFAP’s centrality aligns with its established roles in astrogliosis, neuroinflammation, and BBB disruption after stroke." (PMID 41152969, 2025). "Glial fibrillary acidic protein (GFAP) is an emerging biomarker for the detection of acute intracranial pathology following acute brain injuries such as traumatic brain injury (TBI), stroke, and hypoxic-ischaemic encephalopathy." (PMID 40650780, 2025). "Furthermore, concerning acute ischemic stroke, GFAP may yield insights regarding the duration from onset and the extent of ischemic tissue damage observable through neuroimaging, particularly in instances of stroke with large vessel occlusion." (PMID 40649119, 2025). "Molecular analysis revealed an increase in GFAP as well as in A1 astrocytes and a reduction in A2 astrocytes in the RTN following stroke." (PMID 40586384, 2025). "In a clinical context, blood-based mRNA biomarkers, including glial fibrillary acidic protein (GFAP) and neurogranin (NRGN), have shown potential in predicting stroke severity and functional outcomes." (PMID 40896336, 2025). "GFAP and NSE are important biomarkers used to assess brain injury, especially in neurological disorders like stroke." (PMID 41296388, 2025). "GFAP is elevated in a variety of neurological disorders including traumatic brain injury (TBI), stroke, and neuroinflammatory conditions, potentially confounding its diagnostic utility in AD." (PMID 40943059, 2025). "Other brain-specific biomarkers used following stroke include neuron-specific enolase (NSE), tau, neurofilament light chain (NfL), glial fibrillary acidic protein (GFAP), and ubiquitin C-terminal hydrolase L1 (UCH-L1)." (PMID 39968454, 2025). "A similar pattern was observed 5 days post-stroke (Figures 2EA–EE), with clear GSDMD colocalization with IBA1 and GFAP in brain regions near the hypoxic core." (PMID 39210936, 2024). "Reactive gliosis, indicated by GFAP-positive astrocytes, was markedly evident in CAA mice and CAA mice with stroke." (PMID 38854014, 2024). "Here, we demonstrated the presence of AQP4 and GDNF in ADEV cargo during the first month following stroke, expanding on our previous findings regarding the post-ischemic ADEV profile and the GFAP content of these vesicles." (PMID 39596535, 2024). "Other authors also reported a correlation of GFAP with clinical severity and higher concentrations in ICH compared to AIS and non-stroke patients." (PMID 37483444, 2023). "This study assessed the diagnostic efficacy of selected blood-based biomarkers, including GFAP, NF-L, NT-proBNP, copeptin, neutrophils (%), NLR, and platelet counts, in differentiating IS and HS in the hyperacute phase of stroke." (PMID 37685295, 2023). "A significant difference in serum GFAP levels has been shown between intracerebral hemorrhage (ICH), AIS, and stroke mimics within 2–6 h after symptom onset." (PMID 36604741, 2023). "Blood samples from 74 stroke patients (25 ICH, 49 IS) were analysed with a GFAP cut-off = 0.29 ng/mL." (PMID 37511304, 2023). "Together with GFAP staining, these data suggest that in the absence of TIC cytokines, minimal differences occur in astrocyte GFAP and myeloid cell CD68 protein levels immediately following stroke." (PMID 38240014, 2023). "The median GFAP level for patients with LVO was 267 (IQR 157;646) pg/mL and for stroke mimics (including SDH) 203 (IQR 109;441) pg/mL." (PMID 36604741, 2023). "After stroke onset, the blood–brain barrier (BBB) is disrupted, leading to the release of GFAP into the bloodstream." (PMID 37762122, 2023). "In this study, adult male GFAP-ChR2-EYFP transgenic Sprague-Dawley rats were stimulated by optogenetics at 24, 36, 48, and 60 h after photothrombotic stroke to activate ipsilateral cortical astrocytes." (PMID 37196130, 2023).
Stroke (continued). "Examining the level of astrocyte cytoskeletal elements 7- and 30 days post-stroke, TKO mice had reduced GFAP levels in astrocytes compared to WT mice." (PMID 38240014, 2023). "We further evaluated neuroinflammation profiles by investigating changes in IBA1+ microglia and GFAP+ reactive astrocytes in Veh-, HOE642-, or RIM-treated brains at 3 d post-stroke." (PMID 37686096, 2023). "GFAP in older adults with evidence of high cerebral amyloid burden, TBI, or stroke are consistently shown to be increased." (PMID 37251545, 2023). "Post stroke reactive gliosis was evaluated in 600 × 600 μm ROIs located within motor cortex using IBA1 and GFAP immunohistochemistry detecting microglia/macrophages and reactive astrocytes, correspondingly." (PMID 37658339, 2023). "Overall, the results of the present review are indicative of a link between the circulating levels of BNP, GFAP, RDW, NLR, MMP-9, and AQP4 following stroke and clinical outcome prognostication." (PMID 36278689, 2022). "After stroke, tau, NFL, GFAp and S100B increased in a time dependent manner, while NSE remained constant over time." (PMID 33723754, 2022). "Increased GFAP serum level corresponds with the higher value for NIHSS and correlated with stroke severity and the extent of brain damage in ischemic stroke patients." (PMID 36159395, 2022). "In the photothrombotic stroke model, mice pretreated with PHP.GFAP-IL-2 exhibited reduced macroscopic damage, and a ~30% reduction in infarct size as quantified by combined scar tissue and ischemic tissue identification." (PMID 35618831, 2022). "In the present study, we used (R)-4-ACPBPA and (S)-4-ACPBPA to target GABAC receptors and measured changes in functional recovery, and glial markers, glial fibrillary acidic protein (GFAP), and GAT3 expression after inducing photothrombotic stroke." (PMID 33801560, 2021). "S100B, NSE, GFAP, and MAPT have previously been used as markers of neuronal damage, such as in stroke, traumatic brain injury, and aneurysmal SAH." (PMID 32978732, 2021). "Our findings lead to the proposal that PTX3, expressed by GFAP‐positive astrocytes, plays an important role as an NVU mediator that regulates stroke pathology through its biphasic effects after white matter stroke." (PMID 33314664, 2021). "The immunoreactivity of glial fibrillary acidic protein (GFAP), ionized calcium-binding adaptor protein (Iba-1), and CD31 was assessed 30 days after stroke to investigate if rGDF11 had effects on gliosis, or angiogenesis respectively." (PMID 32365331, 2020). "In the present study, to observe the neurogenesis in ischemic cortex after stroke regulated by IL-17 and As-IV, NPC markers-Nestin, GFAP and Sox2 and immature neuron marker-DCX, and mature neuron marker-NeuN protein expression was chose." (PMID 32818074, 2020). "Glial fibrillary acidic protein (GFAP), MDA, and superoxide dismutase (SOD) activity are important biomarkers in oxidative stress and neuroinflammatory processes after stroke, and they can predict functional outcomes." (PMID 32331285, 2020). "Wild-type rats subsequently received an endothelin-1 (ET1) subcortical stroke and were imaged at days 7 and 28 post-stroke before immunohistochemistry of TSPO, GFAP, iNOS, and the MHCII rat antigen, OX6." (PMID 32990808, 2020). "Principal component analysis (PCA) and correlation analyses demonstrated that stroke-induced significant and predictable morphological changes that demonstrated strong relationships between IBA1+, GFAP+, and NeuN+ areas." (PMID 33551749, 2020). "Expression of protein markers of two cell populations typically present in the glial scar (GFAP for reactive astrocytes and PDGFR-β for stromal cells of pericytic origin) was quantified at post-stroke day 14 in the infarcted and peri-lesional regions." (PMID 31396042, 2019). "We then examined glial fibrillary acidic protein (GFAP) marked reactive astrocytes in control and VPS35CX3CR1 cortical brain in response to ischemia/stroke." (PMID 31771656, 2019).
Stroke (continued). "By Western blotting and the immunohistochemistry of GFAP, we found that MIF treatment obviously increased the gliosis in ipsilateral cortex in stroke model." (PMID 29335619, 2018). "Stroke resulted in an increase in GFAP expression, as assessed 7-days post-stroke following treatment with 1 mg/kg PEG-IGF-I from 3 hrs post-stroke compared to vehicle-treated stroke controls (P < 0.05)." (PMID 28325900, 2017). "Multivariate logistic regression analysis of patients with stroke, including all significant variables, only identified ‘previous history of stroke’ and ‘NIHSS’ as independent predictors of higher GFAP concentrations." (PMID 27074724, 2016). "Consistently, multivariate logistic regression analysis revealed that previous history of stroke and NIHSS were found to independently contribute to the probability of having higher GFAP concentrations when only patients with ischemic stroke were considered." (PMID 27074724, 2016). "This was concurrent with the activity of glial fibrillary acidic protein (GFAP)-positive astrocytes, which mainly localized at the peri-infarct region and significantly increased in number at 11 and 18 days after stroke." (PMID 27316350, 2016). "Like GFAP, numerous experimental and clinical studies have shown increased UCH-L1 levels in cerebrospinal fluid (CSF) and blood of patients following TBI and stroke." (PMID 27074724, 2016). "In this controlled prospective study, we explored two candidate biomarkers for early diagnosis of stroke, namely UCH-L1 and GFAP, which are abundantly expressed in neuronal and glial cell respectively." (PMID 27074724, 2016). "On the one hand, reactive gliosis, indicated by increasing GFAP and AQP4 expression, is a sign of astrocyte swelling at the early stage of mild stroke and in the penumbra of severe stroke." (PMID 27242440, 2016). "A number of clinical research studies explored the use of serum GFAP as a tool for the diagnosis and prognosis prediction in TBI and stroke patients." (PMID 27074724, 2016). "We assessed blood-brain barrier permeability by measuring serum levels of glial fibrillary acidic protein (GFAP), which is a well-known biomarker of brain injuries including stroke and trauma." (PMID 27905989, 2016). "Nevertheless, by describing the kinetics of both GFAP and antibodies against NR2 RNMDA in the following 2 weeks after stroke we demonstrated that used together, the biomarkers can discriminate between the two types of lesions even after the first 12 hrs." (PMID 26081945, 2015). "The levels of GFAP and of antibodies against NR2 RNMDA were measured in blood samples obtained within 12 hrs after stroke onset and 24, 48 and 72 hrs and 1 and 2 weeks later using ELISA immunoassay." (PMID 26081945, 2015). "The mRNA level of glial fibrillary acidic protein (GFAP), a marker of reactive astrogliosis, was upregulated at 7 d after stroke." (PMID 25341035, 2014). "There was also a significant correlation between infarct volume and the number of Ki67/GFAP co-labelled cells within SVZ (r = 0.73, P<0.005, n = 15) 7 days post-stroke." (PMID 24809543, 2014). "We therefore quantified Ki67/GFAP+ cells and DCX+ cells separately along the lateral ventricle in both the ipsilateral and contralateral SVZ 7 days post-stroke at the same anatomical level for all sections (+1.2 mm relative to bregma)." (PMID 24809543, 2014). "Having validated the use of GFAP and PH3 labelling to identify and quantify mitotic NSC, we examined the parts of the SEZ directly affected by ischaemia 4–5 weeks and 1 year after stroke." (PMID 23830949, 2013). "Several biomarkers such as S100β, glial fibrillary acidic protein (GFAP), matrix metalloproteinase-9 (MMP-9), and neuron-specific enolase (NSE) have been extensively studied in stroke." (PMID 23028472, 2012).
Stroke (continued). "This was the case in young and old mice of each gender and increased co-localization of GFAP and CD68 with pSmad2 corresponded with the profile of increased TGFβ signaling after stroke we observed by real time imaging." (PMID 20937129, 2010). "The evidence indicates distinct prognostic patterns: biomarkers of inflammation (e.g., TNF-α, IL-6, IL-1β) and neuronal or glial damage (e.g., S100B, GFAP, NSE, NfL) tend to correlate with less favorable outcomes, especially when measured in the acute phase of a stroke." (PMID 41598337, 2026). "Integrating GFAP and UCH-L1 measurements into emergency protocols may enhance stroke diagnosis, optimize patient triage, and ultimately improve outcomes by facilitating the faster initiation of appropriate therapies." (PMID 40649119, 2025). "In the groups of patients from non-Appalachian counties only GFAP was significantly altered between stroke and control patients, with its expression being elevated in the stroke patients." (PMID 41306424, 2025). "In the non-Appalachian population only GFAP was significantly different between stroke and control groups, with it being elevated in the stroke group." (PMID 41306424, 2025). "Considering recent studies pointing towards sexual dimorphism in glial cell responses after stroke, we further investigated the possible relationships between GPR17+, AIF1+, and GFAP+ cells within the PI area of chronic lesions by performing sex‐specific correlation analyses on our cases." (PMID 39703181, 2025). "The exact role of biomarkers S100B, GFAP and NSE in diagnosing stroke is still being defined." (PMID 41150802, 2025). "In a prior study, a different iteration of the LVOne GFAP LFA, employing a marginally higher threshold of GFAP (0.213 ng/ml) to indicate a positive test result, was used to assess plasma GFAP concentration in patients with suspected stroke." (PMID 40650780, 2025). "Comparing the proportion of GFAP-positive cases between stroke patients (79.7%) and patients without stroke (6.25%), the resulting power was 99%, even for an adjusted significance level of α = 0.02." (PMID 40649119, 2025). "An ultra-early investigation conducted with a mobile stroke unit demonstrated that the median time for blood sampling was 58 min post-symptom onset (ranging from 36 to 133 min), revealing that UCH-L1 and GFAP concentrations increased by as much as tenfold above normal values within just 36 min." (PMID 40649119, 2025). "To assess the effects of pharmacological modulation of FGF21 on the astrocyte response after stroke, we subjected MCAO mice to intraperitoneal treatment with rhFGF21 at 12 h intervals starting after reperfusion and measured GFAP expression in the cortical areas adjacent to the infarcted region." (PMID 40021824, 2025). "We found that PHA treatment reduced GFAP+ astrocytes (p=0.016) in the hippocampi ipsilateral to stroke injury but not CD68+ microglia/macrophages." (PMID 40661422, 2025). "Two studies in stroke did not include a sham group (without MCAO/ICH) when assessing GFAP expression." (PMID 40485663, 2025). "NSE is not specific to stroke and can increase in other CNS disorders, and its levels rise more slowly compared to biomarkers like GFAP or S100B, making it less useful for early stroke diagnosis." (PMID 40142325, 2025). "While there is an increase in GFAP in stroke brains as a marker of injury, there is no MRGPRX2 or tryptase expression, suggesting a lack of MRGPRX2-expressing mast cells in the human brain after stroke, consistent with our mouse data." (PMID 40712576, 2025). "When the with-stroke vs. the without-stroke groups were analyzed, the performance of GFAP in predicting acute stroke was excellent, and the UCH-L1 was very good." (PMID 40649119, 2025). "We demonstrate further by immunofluorescence that these immune cells infiltrate in the stroke hemisphere near the injured, GFAP-positive tissue and do not accrue in the contralateral hemisphere far away from GFAP signal." (PMID 40712576, 2025).